IL10 (interleukin 10)
Diseases named in the same sentence as IL10 in open-access papers (continued):
Sharing a sentence is not in itself a finding about the gene and the disease.
autoimmune disease (continued). "Blocking IL-10 signalling at the time of immunization may therefore have the possibility of inducing autoimmune diseases in immunized patients." (PMID 28810829, 2017). "Indeed, upregulated IL-10 expression has been identified in many human autoimmune diseases and in animal models." (PMID 28415811, 2017). "The heterodimeric IL-35 cytokine, of which p35 is a subunit, has previously been shown to inhibit expansion of pathogenic Th17 cells and to play a critical role in mitigating autoimmune diseases by inducing expansion of IL-10 and/or IL-35-expressing Breg cells." (PMID 29051763, 2017). "Concerns about the development of autoimmune disease may prevent the inclusion of IL-10 inhibitor as a component of a therapeutic vaccine." (PMID 28810829, 2017). "It remains a challenging task to elucidate whether the manipulation of NFATc1 and IL-10 activities, alone or together with those of IL-17 and IL-23, will be of benefit for patients suffering from psoriasis and other autoimmune diseases." (PMID 27222343, 2016). "Interestingly, Bregs are a distinct B cell population with potent immunoregulatory properties; among them, the most well subset characterized is the IL10-producing subset (B10 cells), which plays an important role in autoimmune diseases." (PMID 27807534, 2016). "The unique capacity of B cells to reduce the severity of autoimmune diseases through provision of IL-10 has kindled enormous interest in the identification of the responsible B-cell sub-populations, and the signals controlling their expression of suppressive functions." (PMID 27396388, 2016). "These and further data suggest that the NFATc1-mediated inhibition of IL-10 expression might be of general impact for the development of autoimmune diseases and a novel target how to treat them." (PMID 27222343, 2016). "Thus, we proposed that TLR4 can promote B cells to develop into Bregs to secrete IL-10, thus inhibiting the development of inflammation and autoimmune diseases." (PMID 27868072, 2016). "In addition, there is growing evidence that IL-10-producing B cells also play animportant role in human autoimmune diseases such as lupus and rheumatoid arthritis." (PMID 26244559, 2015). "Furthermore, TNF-α inhibits the anti-inflammatory cytokine Interleukin-10 (IL-10) production, triggering chronic inflammation and autoimmune diseases." (PMID 26312490, 2015). "IL-10 production was found to be higher in rheumatoid arthritis (RA), primary Sjogren’s syndrome (SS), and systemic lupus erythematosus (SLE), pointing to B cell hyperactivity as the cause of these autoimmune diseases." (PMID 26137596, 2015). "These animal studies suggested calcitriol may inhibit autoimmune disease at least in part through a VDR-dependent action on CD4+ T cells to induce IL-10-producing Treg cells." (PMID 25852682, 2015). "The exact contribution that IL-10 provides in other autoimmune diseases is also controversial." (PMID 26137596, 2015). "Therefore, in addition to understanding of the molecular mechanism that regulates the expression of this cytokine, therapeutic strategies to augment IL-10 production in inflammatory and autoimmune diseases have been attracting much attention." (PMID 25896516, 2015). "IL-10-producing B cells have regulatory functions in certain autoimmune disease models." (PMID 25313460, 2014). "Interest in IFNγ/IL-10 co-producing Th1 cells has increased in recent years as these cells have been found to be important regulators of the immune response to several infectious, allergic, and autoimmune diseases." (PMID 24415936, 2014). "Thus, the anti-inflammatory response mediated by IL-10 provides pivotal regulation of suppression of autoimmune disease development." (PMID 24742125, 2014). "Furthermore it has been demonstrated that B cells with IL-10-secreting capabilities often possess the ability to secrete IL-6 as well, and B-cell derived IL-6 plays a prominent role in the pathogenesis of autoimmune diseases." (PMID 24551182, 2014).
autoimmune disease (continued). "Finally, we demonstrate that the secreted, immunosuppressive cytokine IL-10 controls the ability of antigen-specific iTreg cells to suppress autoimmune disease." (PMID 25238105, 2014). "It has been proposed that IL-10 expression was under strong genetic influences, and IL-10 locus may determine the contribution to genetic background for development of autoimmune disease." (PMID 23723980, 2013). "Therefore, it plays an important role in immune and inflammatory process and aberrant expression of IL-10 contributes to the development of autoimmune diseases." (PMID 23936042, 2013). "IL-10-producing B cells (B10 cells) have been shown to play a suppressive role in the peripheral blood of humans, with their numbers and function altered in several autoimmune diseases." (PMID 23189166, 2012). "In each instance, Bregs isolated from IL-10 deficient mice (IL-10-/-) mice failed to suppress the development of autoimmune diseases." (PMID 22315945, 2012). "Human interleukin-10 (IL-10) is such a cytokine that may be used for treatment of many inflammatory and autoimmune diseases due to its immunosuppressive properties." (PMID 23049703, 2012). "It has been reported that IL-10 is useful in the treatment of autoimmune diseases." (PMID 23133752, 2012). "A number of SNPs in IL-10 have been associated with various inflammatory and autoimmune diseases including Behcet’s disease, non-infectious uveitis, severity of Rheumatoid Arthritis, and Type 1 diabetes." (PMID 23094074, 2012). "The five most significant pathways were IL-6 signaling, IL-10 signaling, type I diabetes mellitus signaling (an autoimmune disease involving many of the same pro-inflammatory cytokines seen in the other top pathways), acute phase response signaling, and p38 MAPK signaling." (PMID 21777429, 2011). "In many autoimmune disease models, IL-10 has been shown to be protective." (PMID 20927401, 2010). "It has been considered that IL-10 may be a potential therapeutic in the treatment of autoimmune diseases." (PMID 19771172, 2009). "Therefore, the balance between proinflammatory (IL-2, IFN-γ and TNF) and regulatory (IL-4, IL-10 and TGF-β) cytokines probably determines any predisposition to develop autoimmune disease." (PMID 16759382, 2006). "While the IL-10-producing T cells (Treg/Tr1) are the best characterized regulatory lymphocyte population 37, regulatory B cells (Bregs) that suppress inflammation and autoimmune diseases through production of IL-10 (i10-Bregs) or IL-35 (i35-Bregs) have also been described 25, 38-40." (PMID 40093899, 2025). "However, some reports indicate that IL-10 worsens antibody-mediated autoimmune diseases." (PMID 40095800, 2025). "Regulation in Th17 Cells: In the case of Th17 cells, which are pro-inflammatory and associated with autoimmune diseases like IBD, Blimp-1 makes an important contribution to the ability of these cells to transition from a pathogenic to a regulatory phenotype by promoting IL-10 gene production." (PMID 40002370, 2025). "In addition, in some autoimmune diseases, the regulatory function of IL-10 may be impaired, making inflammation still unable to be effectively controlled even when the IL-10 mRNA expression level is increased." (PMID 38872795, 2024). "Systemic lupus erythematosus is an autoimmune disease, during the course of which the occurrence of hematological and other organ manifestations is a significant clinical problem, and a variety of cytokines, such as IL-4, IL-6, and interleukin 10 (IL-10), can have a significant impact on this." (PMID 38139169, 2023). "Interleukin-10 (IL-10)-producing regulatory T cells (Tregs) play a central role in the maintenance of normal immune homeostasis, and dysregulation of Treg cell development and/or function plays roles both in the development of autoimmune disease and in the progression of cancer." (PMID 36973489, 2023).
autoimmune disease (continued). "Notably, in other autoimmune diseases such as multiple sclerosis, IgA+ B cells are enriched in inflammatory lesions in the CNS in both humans and mice, with a role in attenuating disease via IL-10 production." (PMID 36508037, 2023). "Furthermore, BA induced IL-10+ Bregs in a model of Sjögren’s Syndrome effectively ameliorating the disease, highlighting the potential therapeutic implications of inducing Bregs in autoimmune diseases." (PMID 35333906, 2022). "Thus, MSC-sEVs with high expression of IL-10 might be a novel approach for the treatment of autoimmune uveitis or other autoimmune diseases in human." (PMID 35255957, 2022). "An imbalance between pro-inflammatory TNF-α and anti-inflammatory IL-10 in plasma has been considered a biomarker of suppression of Th1 cell-mediated immunity and exacerbation of Th2 humoral immune response, potentially leading to the development of allergic and autoimmune diseases." (PMID 35448433, 2022). "Therefore, strategies aimed at increasing IL-10 may be effective in the treatment of autoimmune diseases, such as MS." (PMID 35741685, 2022). "However, Treg could control the inflammatory response of autoimmune diseases by secreting anti-inflammatory factors such as IL-10, IL-35, and TGF-β." (PMID 35428280, 2022). "Also, there were reports about increased levels of serum IL-10 during autoimmune diseases." (PMID 35474925, 2021). "IL-10 is a pivotal immunomodulator in infectious diseases, autoimmune disorders, inflammatory bone loss conditions including osteoporosis, but no study to date has ever investigated the significance of IL-10 secreting Bregs in regulating bone health in both in vitro and in vivo conditions." (PMID 34276682, 2021). "Similarly, defective IL-10 can lead to the development of autoimmune diseases." (PMID 35053004, 2021). "However, in recent years, several studies have shown that regulatory B (Breg) cells, an immunosuppressive subset of B cells, may exert protective effects against autoimmune diseases by secretion of inhibitory cytokines such as IL-10." (PMID 34108975, 2021). "Involvement of IL-10–producing Bregs is largely beneficial in protection from excessive immune activation during autoimmune diseases, tumor development, and transplantation; however, they may also contribute to the aggravation of disease by suppressing beneficial T cell–mediated responses." (PMID 34293057, 2021). "Interleukin 27 could limit autoimmune diseases by stimulating IL-10–secreting T cells." (PMID 32849596, 2020). "Thus, strategies designed to increase IL-10 may be effective in the treatment of autoimmune diseases, such as MS." (PMID 32255785, 2020). "Therefore, IL-10 hypomethylation may provide a potential epigenetic marker for clinical prediction of autoimmune diseases." (PMID 32582189, 2020). "Thus, current studies on the functional implications of IL-10+ Th17 cells in the pathogenesis of autoimmune diseases can direct the development of combined therapies for autoimmune diseases and allow for a better understanding of the functional diversity of Th17 cells." (PMID 29892286, 2018). "In humans, impairment of IL-10 production in Bregs could contribute to autoimmune diseases." (PMID 29371592, 2018). "Thus, too much IL-10 may suppress protective T cell responses, while too little IL-10 may contribute to the development/aggravation of autoimmune disorders through an excessive activation of T cells." (PMID 29922853, 2018). "IL-10, as an immunosuppressive cytokine, has an essential role in the establishment of peripheral tolerance to allergens and protects the host from exaggerated inflammatory responses to pathogens as well as autoimmune diseases, and can also inhibit T-cell proliferation and cytokine production." (PMID 28002795, 2017).
autoimmune disease (continued). "Therefore, our findings could mimic the state in several autoimmune diseases with continuously IC-activated pDCs and an increased number of regulatory B cells with impaired capacity to produce IL-10 and suppress extensive immune activation." (PMID 28846748, 2017). "The findings that CD226 ligation could promote IL-10 cytokine secretion led us to further investigate whether CD226 is involved in the development of autoimmune diseases such as EAE, a murine model for human multiple sclerosis, which has been proved to be regulated by Th1/Th17 as well as Tregs." (PMID 26942885, 2016). "Our data suggest that IL-10 production from T cells, possibly Th17cells, may act as a negative regulator to dampen inflammatory response mediated by antigen specific T cells or self-reactive T cells during autoimmune diseases." (PMID 27308096, 2016). "However, it is unclear whether IL-10 changes Th17 differentiation programs or IL-10 shifts pathogenicity of already differentiated Th17 in vivo during immune response or autoimmune disease conditions." (PMID 27308096, 2016). "Breg-mediated amelioration of autoimmune diseases in animal models (e.g. antigen-induced arthritis, collagen-induced arthritis and experimental autoimmune encephalomyelitis) is typically dependent upon IL-10 but besides that relatively little is known about the mechanism of action." (PMID 24551182, 2014). "There is also evidence to support the role of B-cells as immune regulators, because they are able to secrete IL-10 which could prevent inadequate stimulation of the immune system (e.g., autoimmune diseases), and could also serve to limit the aggressiveness of the immune response." (PMID 24288024, 2013). "Mechanisms of how helminth infections provide protection in autoimmune diseases are manifold and comprise immunosuppression attributed to an increased activity of regulatory T cells (Treg cells), alternatively activated macrophages and, more recently, IL-10 producing regulatory B cells." (PMID 23782752, 2013). "Also, we are examining whether these cells may secrete anti-inflammatory cytokines, such as IL-10 among others, notwithstanding the perplexing and highly questionable results, showing that IL-10 is a culprit in another autoimmune disease." (PMID 23430541, 2013). "As IL-10 is crucially involved in preventing excessive immune responses and plays an important role in development of suppressor T cells decrease in its production could lead to autoimmune disease." (PMID 21978263, 2011). "Our data suggest that IL-10 production from T cells, possibly Th17 cells and Tr1 cells, may act as a negative regulator to dampen inflammatory response mediated by antigen specific T cells or self-reactive T cells during autoimmune diseases." (PMID 22163016, 2011). "The ability to induce the production of anti-inflammatory cytokines, such as IL-10, makes ZPSs an attractive molecule for the generation of vaccines that can potentially prevent bacterial infections, inflammatory bowel diseases, and autoimmune diseases, such as multiple sclerosis." (PMID 21234388, 2010). "Therefore, administration and/or localization of IL-10 may be critical in determining its immunoregulatory function in autoimmune diseases of the nervous system." (PMID 19771172, 2009). "Consistent with other autoimmune disorders, PBC pathogenesis involves elevated inflammatory factors (IL-6, IL-8, IL-10, TGF-β) and immune cell infiltration, particularly CD4 + and CD8 + T lymphocytes." (PMID 41144108, 2025). "They downregulate pro-inflammatory mediators such as IL-6 and IL-23 while enhancing IL-10 and TGF-β expression, a shift repeatedly observed across models of autoimmune disease." (PMID 41293163, 2025). "Treg cells primarily prevent excessive immune responses and autoimmune diseases by secreting immunosuppressive factors, such as transforming growth factor-beta (TGF-β) and interleukin-10 (IL-10)." (PMID 40881626, 2025).
autoimmune disease (continued). "The regulatory function of IL-10 from DC-SIGN+ cells is particularly relevant in situations where inflammation needs to be carefully controlled, such as during infections or in autoimmune diseases." (PMID 40076949, 2025). "In the pathogenesis of such severe autoimmune diseases as type 1 diabetes (T1D) and systemic lupus erythematosus (SLE), IL10 plays a multifaceted role." (PMID 39337678, 2024). "We further demonstrate a key role for IL10 in mediating the DUSP6 KO protective effect and consider DUSP6 as a potential target for therapeutic development for RA and other autoimmune diseases." (PMID 38974475, 2024). "IL‐10 can also promote pro‐inflammatory CD8+ T cell activity, and promote an inflammatory response in IL‐10‐positive CD4+ cells, in addition to its expected anti‐inflammatory properties in autoimmune diseases." (PMID 37647453, 2023). "Particularly, in a study it has been proposed a three gene-expression panel that included IL10, OAS2, and CD70 genes that, according to the authors, were able to differentiate SLE patients from control subjects and from patients with other autoimmune diseases." (PMID 36428917, 2022). "Plasmablasts have been shown to express IL-17, IL-10, TGF-β, and function as cellular modulators in infection or autoimmune diseases." (PMID 35123388, 2022). "In autoimmune diseases or immunosuppression during organ transplantation, CD8+CD122+ T cells suppressed other effector T cells by secreting IL-10 or inducing apoptosis through Fas/FasL pathway." (PMID 36333670, 2022). "In mice, the miR-10a targets Prdm1 gene to suppress the production of IL-10 in CD4+ T cells, playing important roles in regulation of intestinal homeostasis and in pathogenesis of autoimmune diseases." (PMID 34950131, 2021). "The secretion of IL10 and TGF-β and the production of Treg cells complement each other, which is the key factor for the feasible treatment of autoimmune diseases." (PMID 34305913, 2021). "Vitiligo is considered to be an autoimmune disease because cytokines such as (IFN)-γ, IL-1, IL-6, IL-8, and IL-10 are overexpressed in lesions, and activated CD8 + T lymphocytes, TH17, and other immune cells are significantly aggregated in the lesion area." (PMID 33790887, 2021). "In the present study, through the analysis of the PPI network of DE mRNAs, we identified several hub genes, including IL6, IL10, and CXCL8, which are important genes in autoimmune diseases and inflammatory pathways." (PMID 34284720, 2021). "MSCs can exert their immune function and relieve autoimmune diseases through PEG2, TGF-β, HGF, IL-10, and IDO, which are found in RA, IBD, and other autoimmune diseases." (PMID 33859701, 2021). "Tregs and the cytokines IL-10 and TGF-β play a protective role by maintaining homeostasis, enhancing immune tolerance, and preventing the onset of autoimmune diseases." (PMID 35126129, 2021). "Similar to IL-10 and TGF-β, IL-35 can also ameliorate autoimmune diseases and promote the development of infectious diseases." (PMID 32764544, 2020). "Interleukin 27 (IL-27) plays diverse immune regulatory roles in autoimmune disorders and promotes the generation of IL-10–producing CD4+ T cells characterized by producing the immunosuppressive cytokine IL-10." (PMID 32849596, 2020). "Interestingly, IL-10R signaling and downstream STAT3 phosphorylation are defective in CD4+ T cells from patients with systemic lupus erythematosus and MS, suggesting that failure of T cell suppression by IL-10 may play an important role in autoimmune disease, including in the CNS." (PMID 32303238, 2020). "In autoimmune diseases of the CNS, patients with MS and NMO had higher IL-10 levels in serum and CSF than those of patients with OND or healthy controls." (PMID 31244763, 2019). "Another possible limitation of using anti-CD38 antibodies in autoimmune diseases is that, as already mentioned, CD38 is also widely expressed by IL-10 producing regulatory B cells." (PMID 31892266, 2019).